BICRA (BRD4 interacting chromatin remodeling complex associated protein)
Description:
Component of SWI/SNF chromatin remodeling subcomplex GBAF that carries out key enzymatic activities, changing chromatin structure by altering DNA-histone contacts within a nucleosome in an ATP-dependent manner. May play a role in BRD4-mediated gene transcription.
Synonyms: GLTSCR1; SMARCK1; CSS12
Tractability: PROTAC: UniProt records ubiquitination sites on it.
Gene: Protein-coding gene on chromosome 19 (47,608,196 to 47,703,277, forward strand). Ensembl gene ENSG00000063169.
Subcellular location: Nucleus
Subcellular location (Human Protein Atlas): Nucleoplasm
Pathways (Reactome):
Chromatin organization: Formation of the non-canonical BAF (ncBAF) complex
Gene Ontology:
Molecular function: protein binding; transcription regulator activator activity
Biological process: positive regulation of DNA-templated transcription; chromatin remodeling; negative regulation of cell differentiation; positive regulation of cell population proliferation; positive regulation of stem cell population maintenance; regulation of transcription by RNA polymerase II
Cellular component: nucleus; SWI/SNF complex; chromatin; GBAF complex; nucleoplasm
Genetic constraint (gnomAD): Loss-of-function variants: 21 observed, 45.89 expected, observed/expected ratio (o/e) 0.46, 90% interval 0.32 to 0.66. The synonymous counts are far from expectation, so gnomAD's model fits this gene poorly and the ratio says little. Missense variants: 1,830 observed, 1,424.6 expected, observed/expected ratio (o/e) 1.28, 90% interval 1.24 to 1.34. Synonymous variants: 1,120 observed, 729.76 expected, observed/expected ratio (o/e) 1.53, 90% interval 1.46 to 1.61.
Gene-disease validity (ClinGen):
ClinGen rates the evidence that BICRA causes each of these diseases.
Coffin-Siris syndrome (autosomal dominant): Definitive. Coffin-Siris syndrome (CSS) is a rare congenital multi-systemic genetic disorder characterized by aplasia or hypoplasia of the distal phalanx or nail of the fifth digit, developmental delay, intellectual disability, coarse facial features, and other variable clinical manifestations.
Homologues: Orthologues: chimpanzee BICRA (99% identical), macaque BICRA (98% identical), dog BICRA (92% identical), pig BICRA (91% identical), rat Bicra (88% identical), mouse Bicra (88% identical), guinea pig BICRA (80% identical), tropical clawed frog bicra (54% identical), zebrafish bicra (40% identical). Paralogues in human: BICRAL (17% identical).
Diseases named in the same sentence as BICRA in open-access papers:
BICRA is named in the same sentence as 38 diseases in open-access papers, as found by Europe PMC text mining. Sharing a sentence is not in itself a finding about the gene and the disease. The quoted sentences say what the papers report.
glioma (11 papers, 2010 to 2025). A benign or malignant brain and spinal cord tumor that arises from glial cells (astrocytes, oligodendrocytes, ependymal cells). "Additionally, the BICRA gene has been associated with glioma tumor suppression." (PMID 39246911, 2024).
Coffin-Siris syndrome 12 (3 papers, 2023 to 2025). "BICRA was first identified as the pathogenic gene for Coffin–Siris syndrome 12 (CSS12; MIM#619325) in nine unrelated patients." (PMID 37485815, 2023).
Borjeson-Forssman-Lehmann syndrome (1 paper, 2021). A X-linked yndrome characterized by intellectual deficit, truncal obesity, characteristic facial features, hypogonadism, tapered fingers and short toes. "Pathogenic variants in the BAF complex are known to cause CSS, Nicolaides-Baraitser syndrome (NCBRS, MIM 601358), Borjeson-Forssman-Lehmann syndrome (BFLS, OMIM 301900), and other CSS-like conditions (BICRA and SMARCD1)." (PMID 35126043, 2021).
epilepsy (1 paper, 2024). A brain disorder characterized by episodes of abnormally increased neuronal discharge resulting in transient episodes of sensory or motor neurological dysfunction, or psychic dysfunction. "This study presents the case of a three-year-old male diagnosed with ASD, developmental speech delay, and epilepsy, with a heterozygous variant of uncertain significance (c.1246G>C, p.Ala416Pro) in the BICRA gene." (PMID 39246911, 2024).
Neurodevelopmental delay (1 paper, 2023). "We reported a de novo BICRA variant that may lead to neurodevelopmental delay." (PMID 37485815, 2023). "BICRA, a transcript regulator, was identified as the genetic factor of Coffin–Siris syndrome 12 (CSS12) recently, which was characterized by diverse neurodevelopmental delays." (PMID 37485815, 2023).
squamous cell carcinoma (1 paper, 2022). A carcinoma arising from squamous epithelial cells.
tumor (13 papers, 2010 to 2025). "Leveraging advanced bioinformatics techniques, the identification of 12 crucial genes (ETNK1, BICRA, IL-1R1, KDM3A, ARID2, GSK3β, EZH2, NOTCH1, SMARCA4, FOS, CREB1, CASP3) associated with the tumor-suppressing miR-101-3p network stands out as a notable achievement." (PMID 40074445, 2025).
cancer (9 papers, 2010 to 2025). A tumor composed of atypical neoplastic, often pleomorphic cells that invade other tissues. "BICRA, a subunit of the ncBAF complex, regulates transcription and epigenetics, processes frequently altered in cancer." (PMID 40074445, 2025). "BICRA’s involvement in epigenetic silencing may influence oncogene activation or tumor suppressor inactivation, contributing to cancer progression." (PMID 40074445, 2025).
Mendelian diseases (1 paper, 2023). "A number of potential OA GWAS effector genes have been identified, including some that have been implicated in Mendelian diseases with joint and skeletal abnormalities, such as BICRA (also known as GLTSCR1), EIF6, CHST3, and FBN2." (PMID 37579195, 2023). "Mutation in the BICRA gene has been implicated in a genetic disorder characterized by a variety of neurodevelopmental phenotypes as well as dysmorphic and orthopedic features such as short stature, scoliosis, radioulnar synostosis, joint laxicity, and hip subluxation." (PMID 37579195, 2023).
neurodevelopmental disorder (1 paper, 2024). A behavioral and cognitive disorder with onset during the developmental period that involves impaired or aberrant development of intellectual, motor, or social functions. "Pathogenic variants in the BRD4 interacting chromatin remodeling complex associated protein (BICRA) are linked to BICRA-related neurodevelopmental disorders." (PMID 39246911, 2024). "Recent evidence has found that mutations in the BICRA gene and the ncBAF-complex are associated with neurodevelopmental disorders, such as SWI/SNF-related neurodevelopmental disorders (SSRIDD)." (PMID 39246911, 2024). "By establishing the importance of BICRA in both human and fruit fly nervous system development, the study strengthens the connection between BICRA mutations and neurodevelopmental disorders." (PMID 39246911, 2024). "This case report aims to highlight a gene associated with BICRA-related neurodevelopmental disorders that is rarely described in ASD patients." (PMID 39246911, 2024). "Variants in this gene are associated with BICRA-related neurodevelopmental disorders." (PMID 39246911, 2024). "Furthermore, the BICRA gene, exclusively involved in the ncBAF complex, adds to the complexity of understanding chromatin remodeling in neurodevelopmental disorders." (PMID 39246911, 2024).
BICRA also shares sentences with these, for which no sentence is quoted: Coffin-Siris syndrome (3 papers); colorectal cancer (3); prostate carcinoma (3); synovial sarcoma (2); acute myeloid leukemia (1); adenocarcinoma (1); Astigmatism (1); astrocytoma (1); autism (1); brain tumors (1); combined immunodeficiency (1); cone-rod retinal dystrophy-2 (1); congenital heart defects (1); developmental delay (1); diabetes (1); endolymphatic hydrops (1); infection (1); Intellectual disability (1); lung carcinoma (1); lymphoma (1); medulloblastoma (1); meningioma (1); multiple myeloma (1); myelodysplastic syndrome (1); Nicolaides-Baraitser syndrome (1); oligodendroglioma (1); prostate adenocarcinoma (1); syndromic intellectual disability (1).